ZDHHC24 (zDHHC palmitoyltransferase 24)
Description:
Probable palmitoyltransferase that could catalyze the addition of palmitate onto various protein substrates.
Tractability: Antibody: UniProt predicts a signal peptide or a membrane-spanning region.
Gene: Protein-coding gene on chromosome 11 (66,520,625 to 66,546,235, reverse strand). Ensembl gene ENSG00000174165.
Subcellular location: Membrane
Subcellular location (Human Protein Atlas): Cytosol; Vesicles
Gene Ontology:
Molecular function: protein binding; protein-cysteine S-palmitoyltransferase activity; palmitoyltransferase activity
Biological process: protein targeting to membrane
Cellular component: endoplasmic reticulum; membrane
Genetic constraint (gnomAD): Loss-of-function variants: 19 observed, 18.5 expected, observed/expected ratio (o/e) 1.03, 90% interval 0.71 to 1.5. The upper end of that interval is the gene's LOEUF score, 1.5, which puts it in group 6 of 6, group 1 being the genes least tolerant of losing a copy. Missense variants: 366 observed, 334.04 expected, observed/expected ratio (o/e) 1.1, 90% interval 1 to 1.2. Synonymous variants: 186 observed, 161.39 expected, observed/expected ratio (o/e) 1.15, 90% interval 1.02 to 1.3.
Homologues: Orthologues: chimpanzee ZDHHC24 (99% identical), macaque ZDHHC24 (99% identical), dog ZDHHC24 (95% identical), guinea pig ZDHHC24 (92% identical), mouse Zdhhc24 (87% identical), rat Zdhhc24 (83% identical).
Diseases named in the same sentence as ZDHHC24 in open-access papers:
ZDHHC24 is named in the same sentence as 5 diseases in open-access papers, as found by Europe PMC text mining. Sharing a sentence is not in itself a finding about the gene and the disease. The quoted sentences say what the papers report.
hepatocellular carcinoma (1 paper, 2025). A malignant tumor that arises from hepatocytes. "For example, a 2024 study in hepatocellular carcinoma showed that the palmitoyltransferases ZDHHC17 and ZDHHC24 can palmitoylate AKT, anchoring it to the plasma membrane and significantly increasing AKT kinase activity." (PMID 40740766, 2025).
Parkinson disease (1 paper, 2022). A progressive degenerative disorder of the central nervous system characterized by loss of dopamine producing neurons in the substantia nigra and the presence of Lewy bodies in the substantia nigra and locus coeruleus. "In contrast, the projected-palmitoylome of DG granule cells which have the highest expression of Zdhhc21, Zdhhc4, Zdhhc24, and Zdhhc8 generated KEGG pathways related to ‘Ribosome’, ‘Cholinergic synapse’, and ‘Parkinson’s disease’." (PMID 35819139, 2022).
ZDHHC24 also shares sentences with these, for which no sentence is quoted: breast carcinoma (1 paper); lymph node metastasis (1); schizophrenia (1).